TRPV1 (transient receptor potential cation channel subfamily V member 1)
Diseases named in the same sentence as TRPV1 in open-access papers (continued):
Sharing a sentence is not in itself a finding about the gene and the disease.
esophagitis (5 papers, 2010 to 2023). An acute or chronic inflammatory disease affecting the esophageal wall. "This sensitized response is possibly due to an increase in the expression of TRPV1 channels in vagal afferent fibers after esophagitis." (PMID 27322240, 2016). "In keeping with this observation, TRPV1 KO mice develop a significantly less severe esophagitis after acid exposure." (PMID 27322240, 2016). "In cat spinal afferents, capsaicin-evoked stimulation of epithelial TRPV1 induces hypersensitivity and esophagitis due to the release of substance P and CGRP from esophageal sensory nerve endings." (PMID 27322240, 2016). "In TRPV1 deficient mice, reflux promoting surgery induces significantly less mucosal injury and inflammation than in WT mice and pretreatment with the TRPV1 antagonist capsazepine in WT mice significantly inhibits esophagitis." (PMID 27322240, 2016). "In wild-type mice administered with TRPV1 antagonist capsazepine and acid suppressants, inflammatory parameters were considerably reduced, suggesting that TRPV1 may play a role in acid-induced oesophagitis." (PMID 36768825, 2023). "Similarly, in a model of rat oesophagitis, SP and isolectin B4-expressing sensory neurons innervating the oesophagus were found to have increased TRPV1 expression in acid-induced oesophagitis." (PMID 36768825, 2023). "Moreover, capsaicin causes enhanced relaxation of smooth muscle contraction in the esophagitis model, which supports the fact that acid reflux increases the expression of TRPV1 in primary afferent nerves." (PMID 27322240, 2016). "Furthermore, TPRV1 has been linked to mucosal inflammation as TRPV1-lacking mice were less prone to develop esophagitis during continuous acid exposure, in comparison with wild types." (PMID 28534850, 2017). "Expression of TRPV1 is up-regulated also in human patients with esophagitis, gastro-esophageal reflux disease and non-erosive reflux disease." (PMID 27322240, 2016).
inflammatory skin disease (5 papers, 2017 to 2025). Inflammatory skin disorders covers a broad category that includes many conditions ranging in severity, from mild itching to grave medical health complications These disorders are common in people of all ages and races. "Topical TRPV1 antagonists are well tolerated and are under investigation for the treatment of inflammatory skin diseases, such as atopic dermatitis (PAC-14028, asivatrep; NCT02583022, NCT02757729, and NCT02965118), where they show promising effects." (PMID 41118703, 2025). "According to the ClinicalTrials.gov database, nearly 100 studies have targeted TRPV1 for various conditions, with a focus on asthma and cough, inflammatory skin diseases, and, in particular, various pain conditions." (PMID 41118703, 2025). "Since eosinophils also express TRPV1 in AD skin, our results indicate an important role of TRPV1 for neuroimmune interaction mechanisms in itchy, inflammatory skin diseases, like AD." (PMID 38339203, 2024). "Our results are regarded as an initial impulse to the development of TRPV1-related treatment for skin inflammatory diseases in the future." (PMID 39469627, 2024). "The following sections illustrate the mechanism and diverse functions in various inflammatory skin diseases and the potential clinical value of TRPV1." (PMID 36874007, 2023). "This review summarizes the structure of the TRPV1 channel and discusses the expression of TRPV1 in the skin as well as its role of TRPV1 in skin aging and inflammatory skin diseases." (PMID 36874007, 2023). "In recent years, a growing number of studies have investigated the potential role of TRPV1 in the pathogenesis of inflammatory skin diseases." (PMID 36874007, 2023). "Furthermore, the role of TRPV1 in skin aging and inflammatory skin diseases is explored." (PMID 36874007, 2023). "In addition to traditional antipruritic therapy (antihistamines) to control itch symptoms, TRPV1 antagonists may be used as a new antipruritic drug to treat inflammatory skin diseases." (PMID 36874007, 2023). "Recently, investigations into ion channels, such as Orai-1, TRPV1, and TRPV3, have shed new light on potential targets for the treatment of inflammatory skin diseases, such as AD." (PMID 29348776, 2017).
kidney damage (5 papers, 2019 to 2025). "The present results are consistent with these findings, as the TRPV1 hyperfunction is associated with activation of inflammatory signals triggering IL-1β release in hyperoxaluria-induced nephropathy." (PMID 34201387, 2021). "Activation of the capsaicin receptor TRPV1 can prevent salt-induced kidney damage in rats and increase glomerular filtration rate (GFR) and renal excretion by increasing natriuresis and diuresis, indications of kidney function." (PMID 31817083, 2019). "Oral administration to SCD mice of the TRPV1 agonist, capsaicin, which activates somatosensory nerves through TRPV1 binding, was shown to dramatically alleviate acute vaso‐occlusive events and to significantly reduce ensuing chronic liver and kidney damage." (PMID 34779027, 2022). "Furthermore, the activation of the Capsaicin receptor TRPV1 induces the improvement of the glomerular filtration rate (GFR), the prevention of salt-induced kidney damage, and the enhancement of natriuresis and diuresis." (PMID 36141454, 2022).
knee osteoarthritis (5 papers, 2016 to 2025). "Complementary to clinical association studies in neuropathic pain and painful knee osteoarthritis, the presented study investigated the consequences of TRPV1 1911 A>G on somatosensory and perfusion function in normal and capsaicin challenged skin of healthy subjects." (PMID 28817717, 2017).
memory impairment (5 papers, 2020 to 2026). "Despite these promising results, the therapeutic window for the beneficial effects of TRPV1 modulators is very narrow and higher doses of TRPV1 blockers such as AMG9810 have been associated with learning and memory impairments in the preclinical studies." (PMID 33330461, 2020). "These cytokines are well-established TRPV1 sensitizers, and their accumulation suggests that chronic hyperactivation of TRPV1 in central circuits may contribute to mood disturbances and memory impairment in T1D." (PMID 41463571, 2025). "More interestingly, genetically upregulating TRPV1 ameliorates deficits in hippocampal LTP and reverses memory impairments in APP23/PS45 mice." (PMID 39468688, 2024). "It is possible that the amygdala function was unlikely impaired and the expression of TRPV1 in the amygdala remained unchanged, thus sevoflurane did not induce memory impairment which was consistent with the previous studies." (PMID 34307363, 2021).
multiple sclerosis (5 papers, 2021 to 2026). A progressive autoimmune disorder affecting the central nervous system resulting in demyelination. "In Multiple Sclerosis (MS), TRPV1 is involved in controlling neuroinflammation." (PMID 41569118, 2026). "In 2018, Flex Pharma published the first results of an exploratory Phase 2 study for multiple sclerosis of FLX-787, a TRPA1/TRPV1 co-activator." (PMID 35877758, 2022).
non-alcoholic fatty liver disease (5 papers, 2016 to 2025). "For example, chronic dietary capsaicin intake prevented non-alcoholic fatty liver disease (NAFLD) in mice through TRPV1-mediated peroxisome proliferator-activated receptor δ (PPARδ) activation." (PMID 37998493, 2023). "Activation of TRPV1 by capsaicin-ameliorated non-alcoholic fatty liver disease in mouse models, and TRPV1-mediated induction of PPARδ and UCP2 likely played a role in this effect." (PMID 27120617, 2016). "Furthermore, the activation of TRPV1 by chronic dietary capsaicin has been shown to enhance autophagy via PPARδ, thereby serving as a preventative measure against non-alcoholic fatty liver disease." (PMID 38255767, 2024). "Activation of TRPV1/UCP2 axis by capsaicin has been reported in several disease models, including nonalcoholic fatty liver disease and diabetic cardiovascular complications." (PMID 37528882, 2023).
renal fibrosis (5 papers, 2013 to 2025). A final common manifestation of a wide variety of chronic kidney diseases characterized by glomerulosclerosis and tubulointerstitial fibrosis. "A pro-fibrotic effect with activation of Smad2/3 signals of the loss of TRPV1 was reported in a mouse model of deoxycorticosterone acetate-salt-induced renal fibrosis and dysfunction." (PMID 29971480, 2018). "On the other hand, TRPV1 activation by TGFβR suppresses progression of renal fibrosis caused by DOCA-induced salt dependent hypertension since in TRPV1 knockout mice fibrosis is reduced." (PMID 24098582, 2013). "Activation of TRPV1 favors renal fibrosis and inhibition of TRPV1 favors pancreatic fibrosis, corneal fibrosis and ocular corneal fibrosis." (PMID 36045746, 2022). "Although previous studies have suggested that transient receptor potential vanilloid-1 (TRPV1) is protective against cardiac and renal fibrosis, its functional role in hepatic fibrosis has remained elusive." (PMID 35909891, 2022). "Thus, TRPV1 is involved in mediating inflammatory response and fibrosis in renal fibrosis, and its activation ameliorates both processes." (PMID 36045746, 2022). "In vitro studies have suggested that TRPV1 may be involved in renal fibrosis through the production of major pro-inflammatory mediators of apoptosis and can protect against renal fibrosis as a prospective regulator of inflammatory processes." (PMID 36045746, 2022). "Moreover, TRPV1 signal supports transforming growth factor β1 (TGFβ1)-mediated myofibroblast transdifferentiation of stromal keratocytes and kidney mesenchymal cells, that accounts for corneal opacification and renal fibrosis." (PMID 29971480, 2018). "Furthermore, TRPV1 activation upregulates TGF-β1 protein expression and can inhibit the TGF-β1 fibrogenic activity by downregulating SMAD2/3; these data suggest that TRPV1 inhibits the TGF- β/SMAD signaling pathway and plays a protective role in renal fibrosis induced by salt-sensitive hypertension." (PMID 36045746, 2022).
sarcoma (5 papers, 2014 to 2025). A usually aggressive malignant neoplasm of the soft tissue or bone. "In mice inoculated with NCTC 2472 cells, an intraperitoneal injection of I-RTX had antinociceptive effects and caused an increase in TRPV1 expression in L2/3/4 small, medium, and large DRGs and peripheral axons ipsilateral to the sarcoma cell injection." (PMID 39940997, 2025). "Nevertheless, TRPV1 protein levels were significantly lower in all the various grades of Type 1 (1, 2 and 3) and both forms of Type 2 EC (sarcoma and carcinosarcoma)." (PMID 40243844, 2025). "Spontaneous pain induced by NCTC 2472 sarcoma cell injection was reduced by oral administration of TRPV1 antagonist ABT-102." (PMID 39940997, 2025). "Initial phenotypic reports of the TRPV1-null mouse appeared to rule out a role for TRPV1 in normal or pathological mechanotransduction, but subsequent studies in inflammatory, nerve injury, muscle injury, sickle cell and sarcoma models have all implicated TRPV1 in mechanical hypersensitivity." (PMID 29497363, 2018). "It is reported that inflammatory hyperalgesia increased TRPV1 expression by about 31% in CGRP-positive subpopulations but this did not occur when sarcoma injection was employed." (PMID 25020137, 2014).
allergic asthma (4 papers, 2016 to 2023). A asthma with a basis in a pathological type I hypersensitivity reaction. "It is concluded that co-exposure to PM2.5 and FA exacerbated allergic asthma through oxidative stress and enhanced TRPV1 activation." (PMID 28931832, 2017). "To determine the role of TRPV1 channels in the rat model of allergic asthma we compare responses in vehicle treated rats with those dosed with a selective TRPV1 antagonist, XEN-D0501." (PMID 27255083, 2016). "In summary, the data suggests that blockade of TRPV1 attenuates the allergic asthma phenotype which is consistent with some previous studies." (PMID 27255083, 2016). "Our data suggests the involvement of TRPV1 in allergic asthma and thus we feel this target merits further investigation." (PMID 27255083, 2016). "Indeed, TRPV1 has been reported to be expressed on many cell types in the airway including those thought to play a key role in allergic asthma such as: mast cells, macrophages, epithelial cells, smooth muscle cells, leukocytes and dendritic cells." (PMID 27255083, 2016). "In conclusion, our data supports the view that targeting TRPV1 could be of clinical benefit in patients with allergic asthma, via a possible role in the modulation of CD4+ T cell function." (PMID 27255083, 2016). "Based on this body of data, we, and others, have hypothesised that TRPV1 plays a role in allergic asthma." (PMID 27255083, 2016). "TRPV1,but not TRPA1, KOs developed an attenuated allergic asthma phenotype although these effects failed to reach statistical significance." (PMID 27255083, 2016).
autism (4 papers, 2008 to 2023). Persistent deficits in social interaction and communication and interaction as well as a markedly restricted repertoire of activity and interest as well as repetitive patterns of behavior. "We have recently demonstrated that the autism gene SHANK3 is expressed by both mouse and human DRG neurons and regulates TRPV1 function in the DRG neurons of both species, offering a novel peripheral mechanism of pain dysregulation in autism." (PMID 28424991, 2018).
Cluster headache (4 papers, 2013 to 2022). A type of headache characterized by repeated attacks of unilateral pain lasting 15 to 180 minutes and associated with local autonomic signs. "Furthermore, calpain was found to mediate capsaicin-induced ablation of transient receptor potential vanilloid subtype 1 (TRPV1)-positive trigeminal afferent terminals, which may mediate the release of calcitonin gene-related peptide (CGRP) and contribute to the pathogenesis of cluster headache." (PMID 36404298, 2022).
Constipation (4 papers, 2014 to 2020). Infrequent or difficult evacuation of feces. "Clinical studies have reported increased TRPV1 expression in constipation patients with intestinal damage." (PMID 30463207, 2018). "Due to the damage of intestines and disorder of movements, constipation patients have a much higher TRPV1 expression." (PMID 25464378, 2014). "Further, LP‐CQPC01‐FSM increased the mRNA and protein expression of Cu/Zn‐SOD, Mn‐SOD, CAT, c‐Kit, SCF, and GDNF and reduced the expression of TRPV1 and NOS relative to those of the mice with untreated constipation." (PMID 31289655, 2019).
Dry skin (4 papers, 2017 to 2022). Skin characterized by the lack of natural or normal moisture. "Our results revealed that the mRNA expression levels of Trpa1 (t8 = 4.798, P = 0.0014), Trpv1 (t8 = 3.258, P = 0.0116), and Trpv4 (t8 = 4.297, P = 0.0026) significantly increased in the DRGs of dry skin-induced chronic itch model." (PMID 35095413, 2021). "In this study, we demonstrated that spinal cord NLRP1 inflammasome-mediated inflammatory processes contribute to dry skin-induced chronic itch by activating TRPV1 channel and plays an integral role in itch transduction." (PMID 32312281, 2020). "The present study demonstrated that NLRP1 inflammasome-mediated inflammatory signal contributes to dry skin-induced chronic itch by TRPV1 channel and plays an important role in itch transduction, and it also connects age and gender to chronic itch." (PMID 32312281, 2020). "In mice of either genotype with dry skin or ACD, AMG9810 markedly reduced spontaneous scratch bouts, suggesting that TRPV1 was indeed involved in the development of chronic itch, at least in dry skin and ACD." (PMID 28701920, 2017). "Combined with our above results, we speculate that NLRP1 inflammasome could contribute to the upregulation of TRPV1 in dry skin induced chronic itch model." (PMID 32312281, 2020).
endometrial cancer (4 papers, 2020 to 2025). Primary or metastatic malignant neoplasm involving the endometrium (mucous membrane that lines the endometrial cavity). "A second aim was to determine if AEA or a TRPV1 agonist have similar or disparate effects on EC cell survival, by comparing the effects of these agonists on endometrial cancer cell survival in vitro." (PMID 40243844, 2025). "TRPV1 expression in patients with endometrial carcinoma (15 Type 1 EC, six Type 2 EC) and six normal patients (atrophic endometria) was assessed using quantitative RT-PCR and immunohistochemistry (IHC)." (PMID 40243844, 2025). "Abnormal expression of TRPV1 is closely related to malignant tumors of the female reproductive system such as breast, ovarian, cervical and endometrial cancers." (PMID 36072430, 2022). "The activation of transient receptor potential cation channel subfamily V member 1 (TRPV1) was fundamental in facilitating CBD’s anti-cancer effects in endometrial cancer cells." (PMID 32708138, 2020). "TRPV1 was upregulated in endometrial cancer cell lines Ishikawa treated with CBD (5 μM)." (PMID 40006844, 2025). "The potential answer lies in the involvement of non-classical cannabinoid receptors (i.e., TRPV1 for AEA), as has been demonstrated in endometrial cancer cell lines and in several other cancers, thereby affecting the balance between cell growth and apoptosis (programmed cell death)." (PMID 40243844, 2025).
endotoxemia (4 papers, 2020 to 2025). "It is interesting to note that the role of TRPV1 in cardiac dysfunction associated with sepsis and endotoxemia is also under investigation." (PMID 32586044, 2020). "Our results suggest that TRPV1-expressing central nervous system neurons also regulate inflammatory responses to endotoxemia and infection." (PMID 35610647, 2022). "We previously reported that exogenously administered NADA exerts strong TRPV1-dependent anti-inflammatory effects early during endotoxemia or polymicrobial abdominal sepsis induced by cecal ligation and puncture (CLP)." (PMID 35610647, 2022). "This study identified both TRPV1 and CGRP receptors as potential therapeutic targets in endotoxemia." (PMID 36589466, 2022). "This increment was correlated with the activation of TRPV1 by the endogenously produced activator 20-HETE leading to the release of calcitonin gene related peptide (CGRP), which protects the heart against the cardiac dysfunction during endotoxemia." (PMID 36589466, 2022).
Fabry disease (4 papers, 2016 to 2021). Fabry disease (FD) is a progressive, inherited, multisystemic lysosomal storage disease characterized by specific neurological, cutaneous, renal, cardiovascular, cochleo-vestibular and cerebrovascular manifestations. "Recent studies have shown that an increased expression of TRPV1 in peripheral nerve terminals mediate thermal nociception in the Fabry disease mouse model." (PMID 32375895, 2020).
Huntington disease (4 papers, 2021 to 2024). Huntington disease (HD) is a rare neurodegenerative disorder of the central nervous system characterized by unwanted choreatic movements, behavioral and psychiatric disturbances and dementia. "Similar antihyperkinetic actions of CB1/TRPV1 coagonists have been reported in a rat model of Huntington’s disease." (PMID 33857021, 2021).